CALR (calreticulin)
Diseases named in the same sentence as CALR in open-access papers (continued):
Sharing a sentence is not in itself a finding about the gene and the disease.
myeloproliferative neoplasm (continued). "The Philadelphia chromosome-negative myeloproliferative neoplasms (MPN) share similar molecular characteristics in that they frequently harbor hotspot mutations in JAK2, CALR or MPL, leading to activated JAK/STAT signaling." (PMID 31071164, 2019). "On the other hand, somatic mutations in the endoplasmic reticulum chaperone gene (CALR) are detectable in a majority of myeloproliferative neoplasms (MPN) patients with non-mutated JAK2 and in a small proportion of MPN somatic mutations in the MPL gene have been also reported." (PMID 31064135, 2019). "However, for reasons still unknown, so far attempts to express the forms of CALR lacking the C-domain found mutated in myeloproliferative disorders in E. coli have been only partially successful and the mutant proteins are available in minuscule amounts (Ann Mulally, personal communication)." (PMID 29218307, 2017). "Type I CALR mutations, but not type II, activate the inositol-requiring enzyme 1α (IRE1α)/X-box binding protein 1 (XBP1) pathway of the unfolded protein response, driving the development of myeloproliferative neoplasms." (PMID 41262532, 2026). "Philadelphia negative myeloproliferative neoplasms (MPN) typically carry a driver mutation in the genes for janus kinase (JAK) 2, in calreticulin (CALR) or in the thrombopoietin receptor (MPL)." (PMID 38885318, 2024). "As mutant calreticulin (CALR) is a common driver of myeloproliferative neoplasms (MPN), we analyzed the impact of oncogenic CALRdel52 on the bone marrow (BM) microenvironment in MPN." (PMID 38885318, 2024). "Instead, in Philadelphia the negative myeloproliferative neoplasm HERC1 level was peculiarly controlled, being very low in Primary Myelofibrosis and significantly upregulated in those Essential Thrombocytemia specimens harboring the mutation in the calreticulin gene." (PMID 33477751, 2021). "Background and Objectives: Philadelphia (Ph)-negative myeloproliferative neoplasms can exhibit defects in Janus kinase 2 (JAK2), Calreticulin (CalR), and MPL genes." (PMID 40572650, 2025). "JAK2, CALR, and MPL genes play pivotal roles in the pathogenesis of BCR-ABL negative myeloproliferative neoplasms." (PMID 33936230, 2021). "Hence, we examined a cohort of 123 myeloproliferative neoplasm (MPN) patients without BCR-ABL1 rearrangement and additional ET patients (n=96) for coexistence of JAK2 and CALR mutations." (PMID 27486987, 2016).
essential thrombocythemia (157 papers, 2014 to 2026). A chronic myeloproliferative neoplasm that involves primarily the megakaryocytic lineage. "CALR mutations, characteristic of essential thrombocythemia and primary myelofibrosis, represent a significant group of MPN cases and, compared with other mutations such as JAK2 or MPL, show distinct clinical and prognostic features." (PMID 39960584, 2026). "Calreticulin (CALR) mutations are detected in around 20% of patients with primary and post-essential thrombocythemia myelofibrosis (MF)." (PMID 39831987, 2025). "Clinically, patients with essential thrombocythemia who are positive for CALR mutations exhibit a lower incidence of thrombotic events." (PMID 38673505, 2024). "The mutation load of CALR alleles increases during the transformation from primary thrombocythemia to AML." (PMID 39300580, 2024). "Calreticulin (CALR) mutations are commonly identified in patients with essential thrombocythaemia or myelofibrosis." (PMID 35672563, 2023). "Patient 2 also with primary thrombocytosis and had a CALR mutation as well as the BRAFV600E mutation." (PMID 37525276, 2023). "Calreticulin (CALR) exon 9 mutations are the second most common mutations in patients with essential thrombocythaemia (ET) and primary myelofibrosis (PMF)." (PMID 35672563, 2023). "Somatic CALR mutations occur in approximately 70% of patients with JAK2 V617F-negative essential thrombocythemia (ET) and primary myelofibrosis (PMF)." (PMID 36359414, 2022). "Significant genetic associations included JAK2 V617F for immune thrombocytopenic purpura (p = 1.24 × 10−13) and a novel CALR loss of function variant for essential thrombocythemia (p = 1.59 × 10−13)." (PMID 35945607, 2022). "In 2013, somatic mutations in calreticulin (CALR) were reported as a driver mutation of essential thrombocythemia." (PMID 35237453, 2022). "Somatic mutations in CALR are found in ∼40% of patients with essential thrombocythemia and primary myelofibrosis." (PMID 35767701, 2022). "Mutations of calreticulin (CALR) are the second most prevalent driver mutations in essential thrombocythemia and primary myelofibrosis." (PMID 34333533, 2021). "Testing for the CALR mutation is included in the updated WHO criteria for essential thrombocythaemia (ET) and primary myelofibrosis (PMF)." (PMID 32929772, 2021). "In this review, we investigated the value of BM, liver, and spleen imaging for diagnosis, prognostication, and response monitoring of the JAK2/CALR/MPL mutation-related MPNs (i.e. essential thrombocythemia (ET), polycythemia vera (PV), and myelofibrosis (MF))." (PMID 33879266, 2021). "Since the discovery of a phenotypic driver mutation JAK2V617F in essential thrombocytosis more than a decade ago, additional gene mutations, including in CALR, MPL, and CBL, have been identified." (PMID 34977055, 2021). "Janus kinase 2 (JAK2) and calreticulin (CALR) constitute the two most frequent mutations in essential thrombocythemia (ET), and both are reported to be mutually exclusive." (PMID 27486987, 2016). "The as yet undescribed scenario of pro-B cell acute lymphoblastic leukemia arising in CALR mutated essential thrombocythemia is presented." (PMID 26904322, 2016). "Mutations of CALR in essential thrombocythemia appear to be associated with a distinct phenotype and a lower risk of thrombosis yet their impact on disease progression is less well defined." (PMID 26904322, 2016). "In 2013, somatic mutations of CALR, the gene encoding calreticulin, have been found in 20% to 25% of patients with essential thrombocythemia (ET) or PMF." (PMID 26468945, 2015). "Mutations within CALR have been shown to occur in 67% of essential thrombocythemia (ET) cases." (PMID 36624378, 2023). "MF with CALR mutation (n = 19, 11%) predominated in post-essential thrombocythemia MF." (PMID 37568719, 2023). "While CALR is annotated in Orphanet as involved in essential thrombocythemia, our variant is novel." (PMID 35945607, 2022).
essential thrombocythemia (continued). "VAT1L is mainly expressed in the brain and CALR mutation status defined subtypes of essential thrombocythemia with substantially different clinical course and outcomes, thus it could be a potential biomarker for myeloproliterative neoplasm." (PMID 29069830, 2017). "A 47-year-old male with CALR-mutated essential thrombocythemia (ET) on chronic aspirin therapy developed progressive headache, drowsiness, nausea, and blindness." (PMID 40395274, 2025). "CALR mutations, primarily associated with essential thrombocythemia (ET) or primary myelofibrosis (MF), occur in about 25% and 35% respectively." (PMID 38885318, 2024). "Surprisingly, although CALR and JAK2V617F mutations act on the same intracellular signaling pathways, the thrombotic risk is significantly lower in patients carrying CALR mutations compared with JAK2V617F in essential thrombocythemia (ET)." (PMID 36908768, 2023). "Frameshift mutations in CALR (calreticulin) are associated with essential thrombocythemia (ET), but the stages at and mechanisms by which mutant CALR drives transformation remain incompletely defined." (PMID 33239297, 2020). "Somatic mutations in the calreticulin (CALR) gene are associated with approximately 30% of essential thrombocythemia (ET) and primary myelofibrosis (PMF)." (PMID 32985500, 2020). "In 2013, somatic CALR mutations were identified in most JAK2-unmutated patients with Essential Thrombocythemia (ET) or Primary Myelofibrosis (PMF) patients." (PMID 31332222, 2019). "Calreticulin (CALR) gene mutations have recently been discovered in about 20%–35% of patients affected by essential thrombocythemia (ET) and primary myelofibrosis (PMF)." (PMID 31067725, 2019). "CALR mutations are detected in approximately one-third of essential thrombocythemia (ET) and primary myelofibrosis patients." (PMID 30926777, 2019). "Interferon-α (IFN) selectively targets the malignant clone in a subset of MPN patients and can induce both haematological and molecular remissions in CALR mutated essential thrombocythemia (ET) patients." (PMID 27764253, 2016). "CALR mutations were identified in 8.4% of cases with essential thrombocythemia (ET) and 5.3% of cases with primary myelofibrosis (PMF)." (PMID 26375990, 2015). "Myeloproliferative syndromes, including essential thrombocythemia, can result from mutations in the JAK2, CALR, and MPL genes, each acting as drivers of the fusion protein BCR-ABL1 to increase cell (platelet as well as leukocyte) production." (PMID 39954672, 2025). "His past medical history included calreticulin (CALR)-positive essential thrombocythaemia (ET) for which he was taking hydroxycarbamide and aspirin." (PMID 41479493, 2025). "Most of essential thrombocythemia (ET) patients have the clone harboring a mutation in one of the JAK2, CALR, or MPL gene, and these clones generally acquire additional mutations at transformation to acute myeloid leukemia (AML)." (PMID 38987297, 2024). "CALR mutations have been described essentially in JAK2 and MPL wild-type essential thrombocythemia and primary myelofibrosis." (PMID 38596359, 2024). "or essential thrombocythemia (n = 82; platelet count (PLT) = 675 ± 225 × 109 l−1 mean ± s.d., 51 with JAK2-V617F, 25 with CALR and 6 with MPL mutations)." (PMID 37620601, 2023). "Cases 1, 2, and 3 were of patients with PV, essential thrombocythemia (ET), and primary myelofibrosis (PMF); NGS detected JAK2 p.H538_K539delinsQL (uncommon), CALR p.E380Rfs*51 (novel), and MPL p.W515_Q516del (novel) mutations." (PMID 37396034, 2023). "Polycythemia vera (PV) and essential thrombocythemia (ET) are diseases driven by canonical mutations in JAK2, CALR, or MPL gene." (PMID 37671053, 2023). "Essential thrombocythemia is a blood cancer characterized by an overproduction of platelets mediated via a pathway in megakaryocytes involving variants of JAK2, MPL, and CALR." (PMID 36979444, 2023).
essential thrombocythemia (continued). "Lastly, murine models of CALR, including a CALRdel52 conditional inducible knock-in mutation in an Mx-Cre model, have again yielded similar findings and revealed progression from essential thrombocythemia (ET) to MF in homozygous mutant mice." (PMID 37760623, 2023). "Conditions prompting genetic testing in this group included essential thrombocythemia (CALR; JAK), colorectal cancer (MSH 2/6, MYC), Friedrich ataxia (FXN), and long QT syndrome (SNTA1)." (PMID 34515987, 2022). "Essential thrombocythemia (ET) is a myeloproliferative neoplasm resulting from driver gene mutations in JAK2, CALR, and MPL in hematopoietic stem cells." (PMID 35624199, 2022). "The major clinical entities are represented by polycythemia vera (PV), essential thrombocythemia (ET), and primary myelofibrosis (PMF), that are caused by driver mutations affecting JAK2, MPL or CALR." (PMID 36499582, 2022). "Since the discovery of JAK2V617F, CALR, and MPL mutations as phenotypic driver mutations in essential thrombocytosis, the diagnostic workup of patients with essential thrombocytosis has been characterized by molecular study." (PMID 34977055, 2021). "A hypercoagulable state occurs in essential thrombocytosis because of the overproduction of hematopoietic cells secondary to the mutation of the JAK2, CALR, or MPL genes." (PMID 34845429, 2021). "Although the number of mutations causing primary thrombocytosis has recently increased, a stepwise approach first targeting the three hot-spot genes JAK2, MPL, and CALR besides screening for BCR-ABL1 seems to be justified." (PMID 33712866, 2021). "The risk of thrombosis is higher in JAK2 mutated PMF compared to CALR mutated PMF, despite the fact that calreticulin mutated patients display higher platelet counts, both in essential thrombocythemia and in PMF." (PMID 33255170, 2020). "Chronic myelogenous leukemia with myeloid fibrosis arising on the background of essential thrombocytosis harboring both BCR-ABL1 fusion and type-1 like CALR mutation." (PMID 32000382, 2020). "Somatic frameshift mutation of the calreticulin gene (CALR) is another MPN-restricted key driver mutation found in 67% and 88% of patients with essential thrombocythemia and primary myelofibrosis respectively." (PMID 32787882, 2020). "Somatic mutations of calreticulin (CALR) have been described in approximately 60–80% of JAK2 and MPL unmutated Essential Thrombocythemia and Primary Myelofibrosis patients." (PMID 31332222, 2019). "CALR mutations are restricted to MPN subtypes displaying aberrant megakaryopoiesis, such as ET, PMF, and post essential thrombocythemia-myelofibrosis (post-ET-MF)." (PMID 27177927, 2016). "In a large single-centre cohort of 298 patients suffering from Essential Thrombocythemia (ET), the JAK2V617F, CALR and MPL mutations were noted in 179 (60%), 56 (18.5%) and 13 (4.5%) respectively." (PMID 26501981, 2015). "The SNP between HBS1L and MYB, rs9376092, has a stronger effect in JAK2V617F-negative cases with somatic CALR and/or MPL mutations and predisposes to essential thrombocythemia in JAK2V617F-positive cases." (PMID 25849990, 2015). "In patients with essential thrombocytosis (ET) and primary myelofibrosis (PMF), acquired mutations in genes such as JAK2 tyrosine kinase, calreticulin (CALR), and myeloproliferative leukemia virus (MPL) have been described." (PMID 25144224, 2014). "Essential thrombocythemia (ET) is a blood cancer caused by mutations in JAK2 and CALR." (PMID 38672593, 2024). "Furthermore, when polycythemia and/or essential thrombocytosis coincide with HE, testing for the JAK2 V617F mutation, CALR, and MPL mutations is recommended." (PMID 39056762, 2024). "In addition, in patients with mutant (mut)CALR‐driven essential thrombocythaemia (ET) and myelofibrosis, there is a direct pro‐inflammatory effect of the mutant protein itself, as secreted mutCALR exaggerates cytokine production from normal monocytes." (PMID 34618358, 2022).
essential thrombocythemia (continued). "CALR mutation is associated with a rapid development of clonal dominance in comparison to JAK2V617F, with high allele burdens in granulocytes of patients in essential thrombocythemia." (PMID 32823933, 2020). "The majority of patients with essential thrombocythemia (ET) show somatic mutations of JAK2, CALR, or MPL." (PMID 40190073, 2025). "Essential thrombocythemia (ET) includes the JAK2 -, CALR-, and MPL-mutated subtypes, and a triple-negative (TN) ET subtype, which lacks these canonical drivers." (PMID 41268701, 2025). "These disorders, which include polycythemia vera (PV), essential thrombocythemia (ET), and primary myelofibrosis (PMF), are driven by acquired somatic mutations in genes such as JAK2, CALR, or MPL, leading to hyperactivation of the JAK/STAT signaling pathway." (PMID 40646529, 2025). "Suspicious of essential thrombocythemia, genomic DNA analysis of the peripheral blood sample showed no pathogenic mutations regarding Janus kinase-2 (JAK2) V617F, JAK2 exon 12, calreticulin (CALR) exon 9, and myeloproliferative leukemia virus oncogene (MPL) W515L/K." (PMID 40385891, 2025). "In addition, studies have shown that in patients with essential thrombocythemia and CALR mutation, there is no benefit from using low-dose aspirin, which is in contrast to patients with a JAK2 mutation." (PMID 39759619, 2024). "Our work was focused on the study of essential thrombocythemia (ET) and primary myelofibrosis (PMF), two MPNs that can be caused by mutations in CALR, the gene encoding calreticulin." (PMID 39519157, 2024). "The co-occurrence of CALR and ASXL1 mutations has been reported to be enriched in patients affected by essential thrombocythemia (ET)." (PMID 37749078, 2023). "MPNs including polycythemia vera (PV), essential thrombocythemia (ET), and MF are characterized by overactive Jak/Stat pathway signaling, usually resulting from mutations in JAK2, MPL, or CALR." (PMID 37760623, 2023). "The classical Philadelphia (Ph) chromosome-negative MPNs comprise polycythemia vera (PV), essential thrombocythemia (ET), and primary myelofibrosis (PMF), and are associated with the driver genes JAK2, CALR, and MPL." (PMID 35805191, 2022). "Chronic myeloid leukemia (CML) is characterized by the BCR–ABL1 fusion gene mutation whereas polycythemia vera (PV), essential thrombocythemia (ET) and myelofibrosis (MF) are typically characterized by the presence of JAK2, CALR, or MPL gene mutations." (PMID 33923680, 2021). "Essential thrombocythemia (ET) is comprised among chronic myeloproliferative neoplasms (MPN) and is caused by driver mutations in JAK2, CALR, and MPL, which lead to megakaryocyte proliferation and prominent thrombocytosis." (PMID 32425934, 2020). "Interestingly, most of the patients were diagnosed with PMF or post-essential thrombocythemia myelofibrosis, either before or after CML diagnosis, suggesting that reticulin fibrosis was the most common phenomenon in patients with concurrent CALR mutation and BCR-ABL1 fusion." (PMID 32000382, 2020). "The most evident demonstration for a pathological role of CALR in cancer etiology is provided by the observation that mutations in exon 9 of CALR are found in the Philadelphia-negative myeloproliferative neoplasms essential thrombocythemia and primary myelofibrosis lacking JAK2V617F mutations." (PMID 29218307, 2017). "MPN, including polycythemia vera, essential thrombocythemia, and primary myelofibrosis are clonal diseases of hematopoietic progenitor cells associated with common mutations in the Janus kinase 2 (JAK2) gene, the gene encoding the thrombopoietin receptor (MPL), and the calreticulin (CALR) gene." (PMID 29143804, 2017). "Calreticulin (CALR) and JAK2-V617F gene mutations, which are major genetic mutations in patients with primary myelofibrosis (PMF) and essential thrombocythemia (ET), exert different effects on the clinical features and outcomes of these diseases." (PMID 27504244, 2016).